RFC2 (replication factor C subunit 2)
Diseases named in the same sentence as RFC2 in open-access papers (continued):
Sharing a sentence is not in itself a finding about the gene and the disease.
Pca (1 paper, 2023). "By analyzing its expression level, function, and clinical role in Pca progression, we demonstrated that RFC2 would be a useful biomarker associated with poor outcomes of patients with Pca." (PMID 37950047, 2023). "Taken together, our findings indicated that increased RFC2 expression is involved in acquiring resistance to ADT in Pca progression to CRPC." (PMID 37950047, 2023). "By combining both KEGG analysis and GO term analysis, seven genes (RNASEH2A, RFC2, RFC4, LIG1, POLD1, POLD2, and POLE4) were identified as new biomarker genes upregulated in CRPC compared to localized Pca and associated with DNA replication and DNA repair." (PMID 37950047, 2023). "We then focused on RFC2 as the most promising DDR-related biomarker because mRNA expression level of RFC2 is upregulated in CRPC tissue compared with Pca, as validated by qRT-PCR analysis." (PMID 37950047, 2023). "To further explore the clinical significance of RFC2 expression in Pca progression, we performed IHC analysis using tumor tissues obtained from 103 patients with localized Pca patients who had undergone radical prostatectomy." (PMID 37950047, 2023). "Notably, IHC analysis showed that high expression of RFC2 was correlated with poor prognosis of Pca patients." (PMID 37950047, 2023). "Thus, our findings indicate that the upregulation of RFC2 could be a useful biomarker of Pca progression." (PMID 37950047, 2023). "Overexpression of RFC2 could serve as a biomarker correlated with Pca progression." (PMID 37950047, 2023). "Western blotting demonstrated that RFC2 was highly expressed in CRPC model cells (22RV1, DU145, and PC3) compared with hormone-sensitive Pca cells (LNCaP), in line with the high mRNA expression levels in CRPC tissues." (PMID 37950047, 2023). "We identified six DDR-related genes (Ribonuclease H2 Subunit A (RNASEH2A), replication factor C subunit 2 (RFC2), RFC4, DNA Ligase 1 (LIG1), DNA polymerase D1 (POLD1), and DNA polymerase E4 (POLE4)) that were upregulated in CRPC compared with Pca tissues." (PMID 37950047, 2023). "Another limitation is that multivariate study by using TCGA data including gene expression profile at mRNA level in Pca tissues suggested that high expression of RFC2 mRNA was not independent prognostic factor for progression-free survival." (PMID 37950047, 2023).
prostate carcinoma (1 paper, 2023). A carcinoma that arises from epithelial cells of the prostate gland. "Our cell growth assay and clinical data suggested that RFC2 is necessary for prostate cancer cell growth." (PMID 37950047, 2023). "Thus, future RFC2 IHC study using other cohorts, including those from other countries, would be helpful for understanding the importance of RFC2 in pathogenesis of advanced prostate cancer." (PMID 37950047, 2023).
tumor (15 papers, 2014 to 2025). "Taken together, these results indicated that RFC2 was closely associated with many oncogenic pathways involved in carcinogenesis and tumor progression in LGG." (PMID 35210438, 2022). "All three upregulated genes showed significantly increased expression in tumor tissues, with fold changes of 4.2 (RFC2, p=0.007), 3.7 (HSP90AB1, p=0.011), and 3.4 (YWHAZ, p=0.015), respectively." (PMID 41164201, 2025). "Our results revealed that RFC2 expression is insignificant in typical vs. tumor of CRC patients and high intensity in IHA protein analysis." (PMID 38504096, 2024). "To evaluate the potential predictive effect of RFC2 on the sensitivity to immune checkpoint inhibitors, we analyzed the associations between RFC2 expression and TMB, tumor MSI, and MMR genes in LGG and other cancer types." (PMID 35210438, 2022). "Among the ten tumor-related genes used in the risk model, TRIM15, NEK6, ISG15, RFC2, and NR1H3 were upregulated." (PMID 36189312, 2022). "Further, we also analyzed the correlations between RFC2 expression and tumor mutation burden (TMB), tumor microsatellite instability (MSI), and mismatch repair (MMR) genes across pan-cancer." (PMID 35210438, 2022). "The mRNA expression of RFC2 was significantly correlated with the individual cancer stage in HCC, and patients in the advanced stage of tumor tended to express higher mRNA expression of RFC2." (PMID 34022962, 2021). "Other genes such as LRRC8E, HNMT, and RFC2 were downregulated in the tumor buds but upregulated in the microenvironment." (PMID 28687755, 2017). "Treatment with 740Y-P (PI3K activator) abrogated phenomena induced by silencing of RFC2, demonstrating that RFC2 could regulate malignant progression of tumor cells through PI3K/AKT/mTOR pathway." (PMID 37821801, 2023). "Among them, RFC2 has been proven to promote a variety of tumor proliferation." (PMID 34022962, 2021). "Patients with advanced cancer and high tumor grade tend to express higher RFC2 mRNA." (PMID 34022962, 2021). "The RFC family consists of five protein subunits, RFC1, RFC2, RFC3, RFC4, and RFC512; which are strongly connected with tumor growth and metastasis." (PMID 38504096, 2024). "In summary, our results show that the transcription and protein of RFC2 in HCC are overexpressed, which is significantly related to the clinical individual cancer stage and pathological tumor grade of HCC patients." (PMID 34022962, 2021). "The transcription and protein level of RFC2 in HCC were overexpressed, which was significantly related to the clinical individual cancer stage and pathological tumor grade of HCC patients." (PMID 34022962, 2021). "The expression of replication factor C complex (RFC2, RFC3 and RFC4) is indicative of proliferative potential (high cell division rates) of BRCA1 tumours." (PMID 25521701, 2014). "Notably, the A2 tumor area exhibited significant reductions in proteins essential to the DNA replication pathway, including MCM3, MCM4, POLD1, RFC2, and PCNA, all of which are pivotal for maintaining the integrity of DNA replication." (PMID 40076915, 2025). "Taken together, these findings suggested that RFC2 levels might be used to assess the TBM levels and MSI status, thereby being established in combination with them as new thresholds to predict the anti-tumor immune response of ICB in LGG and other cancer types." (PMID 35210438, 2022). "However, the expression levels of RFC1, RFC2, RFC3, and RFC4 did not exhibit significant differences in various tumor stages." (PMID 38504096, 2024).
cancer (13 papers, 2008 to 2026). A tumor composed of atypical neoplastic, often pleomorphic cells that invade other tissues. "Further, we proceeded to evaluate the associations between RFC2 expression and immune checkpoint genes expression in pan-cancer." (PMID 35210438, 2022). "In conclusion, our comprehensive pan-cancer analysis discovered for the first time that RFC2 was generally highly expressed in multiple cancer types, including LGG." (PMID 35210438, 2022). "Previous limited studies hinted that RFC2 exerted a potential carcinogenic role in several cancer types, including CRC18, HCC19, and ESCC24." (PMID 35210438, 2022). "Our present study verified that the expression levels of RFC2 were positively correlated with TMB in 18 cancer types and negatively related with that in THYM and ESCA." (PMID 35210438, 2022). "Recently, some reports demonstrated that the aberrant expression of RFC2 was closely involved in the progression and metastasis of several cancers." (PMID 35210438, 2022). "Given the limitations of normal samples in TCGA database, we matched the normal tissues of Genotype-Tissue Expression (GTEx) with the cancer tissues of TCGA to fully reflect the expression landscape of RFC2." (PMID 35210438, 2022). "In the present study, we confirmed that RFC2 was generally up-regulated at both the mRNA and protein levels in a broad set of human cancers, including LGG." (PMID 35210438, 2022). "Taken together, these results indicated that RFC2 served as a powerful prognostic biomarker in multiple cancer types, especially in LGG." (PMID 35210438, 2022). "The results revealed a significant differential expression of RFC2 protein between multiple cancer tissues and corresponding normal tissues." (PMID 35210438, 2022). "RFC2, CHEK1, PCNA, and POLE2 were also associated with worse overall survival in several types of cancer (Group A and D)." (PMID 34853396, 2021). "The transcription of RFC2 in various types of cancer was first analyzed and compared with normal tissues through ONCOMINE database." (PMID 34022962, 2021). "Our results showed that RFC2 was widely highly expressed in most types of cancer." (PMID 35210438, 2022). "Firstly, we examined RFC2 expression levels in pan-cancer tissues based on Oncomine analysis." (PMID 35210438, 2022). "Besides, RFC2 expression was also closely associated with MSI in LGG and another 9 types of cancers." (PMID 35210438, 2022). "Also, previous studies have shown that RFC2 is involved in three of the most significant pathways related to cell cycle regulation and DNA damage repair through 15 pan-cancer pathways relevant to drug response." (PMID 29247873, 2017). "Moreover, we next conducted the functional enrichment analyses of RFC2 in LGG and found that RFC2 was mainly enriched in cancer-related pathways, including cell division, mitotic nuclear division, DNA replication, cell cycle checkpoints, and drug metabolism-related pathways." (PMID 35210438, 2022). "Consistent with transcriptomic data, RFC2, HSP90AB1, and YWHAZ were significantly elevated in cancer patients (e.g., RFC2: 18.6 ± 2.1 ng/mL in patients vs. 8.2 ± 1.4 ng/mL in controls, p < 0.001)." (PMID 41164201, 2025). "Furthermore, as the DNA single-strand break repair pathway is essential for cell survival as an alternative pathway in cancer cells with BRCA mutations, inhibition of the NER pathway by RFC2 in addition to PARPi may have additional therapeutic efficacy for CRPC treatment." (PMID 37950047, 2023). "Our study demonstrated tightly relationships between RFC2 expression and TMB and MSI across various cancers." (PMID 35210438, 2022). "Therefore, RFC2 may play an oncogene in a variety of malignant tumors." (PMID 35483337, 2022). "Based on Oncomine, TCGA, GTEx, TIMER, GEPIA, and HPA databases, we evaluated RFC2 expression levels and its clinical prognostic value in LGG and other cancers." (PMID 35210438, 2022).
cancer (continued). "Then, the mRNA expression of RFC2 was further measured through UALCAN based on level 3 RNA-seq and clinical data of 31 types of cancer from the Cancer Genome Atlas (TCGA) database, which was different from the ONCOMINE database." (PMID 34022962, 2021). "Furthermore, The KEGG pathway analysis showed that RFC2 was mainly enriched in cell cycle, pathways in cancer, HTLV-I infection, oocyte meiosis, and microRNAs in cancer terms." (PMID 35210438, 2022). "RFC2 levels were also correlated with TMB and MSI across various cancers." (PMID 35210438, 2022). "In addition, we also noted a positive correlation between RFC2 levels and MMR genes in most cancers, including LGG." (PMID 35210438, 2022). "Comparatively, RFC2 has a high possibility of interacting with USP10 and belongs to the replication factor C family, which has been reported to promote cell invasion and migration of various cancers." (PMID 35791074, 2022).
infection (1 paper, 2020). The state of being infected such as from the introduction of a foreign agent such as serum, vaccine, antigenic substance or organism. "Our data suggest that the accessory components (RFC2, RFC3, RFC5, PCNA), polymerases (POLD1, POLD2, POLD3, POLE, POLE2, POLE4), and ligase LIG1, were downregulated during infection, for which the downregulation of RFC5, POLD1, POLD2, POLD3, POLE, and LIG1 was CagA-related." (PMID 33339161, 2020).
neurodevelopmental disorder (1 paper, 2024). A behavioral and cognitive disorder with onset during the developmental period that involves impaired or aberrant development of intellectual, motor, or social functions. "Also, we identified six patients with intragenic variants within RFC2, suggesting a potential role for RFC2 in neurodevelopmental disorders, including ADHD, speech delay, and ASD." (PMID 39368701, 2024).
RFC2 also shares sentences with these, for which no sentence is quoted: gastric cancer (2 papers); allergic rhinitis (1); cervical cancer (1); Diamond-Blackfan anaemia (1); esophageal adenocarcinoma (1); head and neck cancer (1); kidney cancer (1); lymphoid neoplasm (1); mesothelioma (1); myeloma (1); neurological diseases (1); ocular melanoma (1); ovarian carcinoma (1); pancreatic cancer (1); pheochromocytoma (1); Right ventricular hypertrophy (1); skin cutaneous melanoma (1); testicular germ cell tumor (1); thrombosis (1); thymoma (1); type 2 diabetes mellitus (1); uterine carcinosarcoma (1).